IRS2 (insulin receptor substrate 2)
Diseases named in the same sentence as IRS2 in open-access papers (continued):
Sharing a sentence is not in itself a finding about the gene and the disease.
prostate carcinoma (18 papers, 2009 to 2025). A carcinoma that arises from epithelial cells of the prostate gland. "Our comprehensive study on the AR/IRS2/PI3K/AKT axis also provides theoretical support for the development of more effective treatment strategies for prostate cancer." (PMID 41050263, 2025). "To examine the impact of HIC1/AR/IRS2 on the progression of castration‐resistant prostate cancer, we injected HIC1‐silenced cells (LNCaP‐sh‐HIC1) and a control group (LNCaP‐sh‐NC) labeled with fluorescence into the posterior lobe of the prostate." (PMID 41050263, 2025). "This study sheds light on the involvement of HIC1 in prostate cancer and proposes that the regulation of the AR/IRS2 axis represents a potential mechanism through which HIC1 impacts the development of prostate cancer." (PMID 41050263, 2025). "Increased expression and activity of IRS2 are commonly observed in various cancers, including prostate cancer, along with enhanced activation of the PI3K/AKT pathway." (PMID 41050263, 2025). "HIC1 inhibits AR expression to suppress the development of castration‐resistant prostate cancer through the IRS2/PI3K/AKT axis." (PMID 41050263, 2025). "This study reveals that HIC1 inhibits the progression of prostate cancer by regulating the AR/IRS2 axis, thus addressing a research gap and enhancing our understanding of HIC1's mechanism of action." (PMID 41050263, 2025). "Recently, we showed that IRS-2 promotes the secretion of matrix metalloproteinase-9 (MMP-9) in the PC3 cell line, a malignant prostate cancer cell line expressing high levels of IRS-2." (PMID 39859555, 2025). "IRS-2 protein levels are high in PC3 and DU145, but lower in LNCap compared to PC3 cells, indicating that IRS-2 protein levels are correlated with the malignancy of prostate cancer cell lines." (PMID 37894751, 2023). "The expression levels of IRS-2 have been examined in human prostate tumors and several prostate cancer cell lines." (PMID 37894751, 2023). "IRS-2 expression levels are low in LNCap cells, which represents an indolent form of prostate cancer, while IRS-2 expression levels are high in PC3 and DU145 cells, which are highly aggressive prostate cancer cell types." (PMID 37894751, 2023). "In the present study, we identified a novel role of IRS-2 in promoting the secretion of MMP-9, which causes activation of the IGF signaling pathway in human prostate cancer cells, PC3." (PMID 37894751, 2023). "Taken all together, our findings indicate that USP9X is required for the promotion of prostate cancer growth by maintaining the activation of the Erk1/2 pathway through IRS-2 stabilization." (PMID 30338032, 2018). "On the other hand, in another prostate cancer cell line LNCaP, IRS-2 protein level was too low to detect, suggesting that the dependency on IGF-IR/IRS-2 pathway is lower in LNCaP than PC3." (PMID 30338032, 2018). "In the present study, we revealed that the IGF-IR/IRS-2 pathway, which requires a high level of IRS-2 protein, is critical for anchorage-independent growth in human prostate cancer cell line PC3." (PMID 30338032, 2018). "Although the Human Protein Atlas database showed IRS-2 protein level was not different between normal and prostate cancer tissue (data not shown), it has been reported that in a portion of human prostate cancer tissue, IRS-2 protein level is up-regulated." (PMID 30338032, 2018). "In this study, our findings provided the first evidences that USP9X regulates the protein level of IRS-2, and therefore regulates the IGF-IR/IRS-2/Erk1/2 axis in PC3 human prostate cancer cells." (PMID 30338032, 2018). "CASP3 rs4862396, BMP5 rs3734444 and IRS2 rs7986346 were found to be the independent prognostic markers for patients receiving ADT for prostate cancer." (PMID 22844442, 2012). "Deletion of IRS2 has been found to suppress prostate cancer cell growth, proliferation and invasion in PTEN+/− mice by decreasing MYC expression and DNA synthesis." (PMID 22844442, 2012).
prostate carcinoma (continued). "Expression of both IRS-1 and IRS-2 is reported to be increased in hepatocellular, pancreatic and prostate cancer and malignant pleural mesothelioma." (PMID 19534786, 2009). "Moreover, we have previously reported that IRS-2 promotes MMP-9 secretion in the prostate cancer cell line PC3 and induces cancer cell overgrowth and malignant transformation." (PMID 39859555, 2025). "Also, the association of Nedd4 and IRS2 through monoubiquitination has been reported to activate IGF-1 signaling and induce cell proliferation in prostate cancer cells." (PMID 38272982, 2024). "The IRS-2 levels were positively correlated with Gleason grade in human prostate cancer tissues." (PMID 37894751, 2023). "In addition, a positive correlation was observed between IRS-2 protein levels and Gleason grade in human prostate cancer tissue." (PMID 37894751, 2023). "It was reported that miRNA-338-3p could directly target PREX2a, MACC1, Rab14, RAB23, IRS2, and Sox4 in ovarian cancer, gastric cancer, breast tumor, prostate cancer, non-small cell lung cancer, glioblastoma, and neuroblastoma." (PMID 33817311, 2021). "In addition to regulating Lin28, let‐7 miRNAs directly target and repress the expression of Irs2, a positive regulator of cell proliferation upregulated in liver, pancreas, and prostate cancer." (PMID 32985705, 2020). "In addition to prostate cancer, previous reports have shown that in human endometrial cancer, leiomyosarcoma and several cell lines of various human cancer, IRS-2 protein level is up-regulated." (PMID 30338032, 2018). "In addition, by using PC3 human prostate cancer cells, we revealed that IRS-2 stabilization by USP9X is required for the constitutive activation of Erk1/2." (PMID 30338032, 2018). "Taken together, IRS-2 protein may be up-regulated preferentially in highly malignant types of prostate cancer, and therefore the dependency on IGF-IR/IRS-2 pathway may be high especially in such type of prostate cancer." (PMID 30338032, 2018). "It suggested that CASP3 rs4862396, BMP5 rs3734444 and IRS2 rs7986346 may be useful markers for predicting the survival in patients receiving ADT for prostate cancer." (PMID 22844442, 2012). "Our results suggest that CASP3 rs4862396, BMP5 rs3734444 and IRS2 rs7986346 may affect the survival in patients after ADT for prostate cancer, and the analysis of these SNPs can help identify patients at higher risk of poor outcome." (PMID 22844442, 2012). "For example, the reference DHS re13.110396155 (located ~10 kb upstream of the prostate cancer associated IRS2 gene) presents as a DHS in PrEC but not in LNCaP, and accordingly, WGBS data show the region to be lowly methylated in PrEC and highly methylated in LNCaP." (PMID 27717381, 2016). "Therefore, rs7986346 might regulate IRS2 expression and affect prostate cancer progression to castrate resistance." (PMID 22844442, 2012). "In this context, previous publications demonstrated that USP9x-dependent stabilization of insulin receptor substrate 2 or the transcription factors PBX homeobox 1 and ERG supported prostate cancer growth and metastasis." (PMID 37173959, 2023). "Insulin receptor substrate-2 (IRS-2), a substrate of the insulin-like growth factor (IGF)-I receptor, is highly expressed in the prostate cancer cell line, PC3." (PMID 37894751, 2023). "For example, in prostate cancer, TMPRSS2-IRS2UIB fusion resulted in the upregulation of IRS2, an important tumor driver in colon cancer." (PMID 32631391, 2020). "In prostate carcinoma cells, IRS-1:IRS-2 ratios are lower in malignant vs. benign prostate tissue and decreased IRS-1 expression is associated with increased motility and invasion, functions associated with later disease stages." (PMID 31393907, 2019). "It has been also reported that in human prostate tumor and several prostate cancer cell lines including PC3, the expression of IRS-2 is elevated." (PMID 30338032, 2018).
prostate carcinoma (continued). "In a human prostate carcinoma cell line, small interfering RNA (siRNA)-mediated knockdown of USP9X reduced IGF-IR as well as IRS-2 protein levels and increased their ubiquitination." (PMID 30338032, 2018). "Furthermore, the IRS2/PI3K/AKT axis, which involves the insulin receptor substrate 2 (IRS2) signaling pathway, the phosphoinositide 3‐kinase (PI3K), and protein kinase B (AKT), plays a crucial role in prostate cancer development." (PMID 41050263, 2025). "We recently discovered that IRS-2 is not highly expressed in androgen-dependent prostate cancer LNCaP cells." (PMID 37894751, 2023). "Thus, it is likely that at least in a portion of human prostate cancer, USP9X interacts with IRS-2 resulting in its deubiquitination and stabilization, followed by the maintenance of high protein level of IRS-2." (PMID 30338032, 2018). "In addition, IRS2 promotes cell motility and invasion in neuroblastoma and mesothelioma cells, while overexpres­sion of IRS1 in prostate carcinoma cells decreases tumor cell motility." (PMID 23112878, 2012). "In contrast to IRS-2, IRS-1 may suppress cell migration because expression of IRS-1 in LnCAP prostate carcinoma cells decreases their motility." (PMID 19534786, 2009). "Thus, the expression levels of IRS-2 and MMP-9 were examined in human prostate cancer tissues." (PMID 37894751, 2023). "However, IRS2 only binds to USP15 after it is connected to the ubiquitin molecule, thereby blocking IGF1-dependent IRS2 phosphorylation to weaken IGF-I signaling in prostate cancer PC-3 cells." (PMID 35203682, 2022). "The other prostate cancer DU145 cells, which are malignant similar to PC3, expressed high levels of IRS-2 similar to PC3 but did not secrete MMP-9." (PMID 37894751, 2023).
Hepatic steatosis (16 papers, 2012 to 2024). Steatosis is a term used to denote lipid accumulation within hepatocytes. "Thus, in vivo hypoinsulinemic T1FLD mice developed hepatic steatosis, which was associated with an up-regulation of IRS-2 relative to IRS-1, and an increase in FATP-2 and FATP-5 mRNA expression, as well as greater FATP-2 protein levels." (PMID 22745692, 2012). "On the other hand, activation of the Hippo pathway prevented fatty liver and liver cancer by inhibiting IRS2/AKT pathway." (PMID 32169080, 2020). "Moreover, miR-27b-5p has been reported to bind directly to insulin receptor substrate 2 (IRS2), inhibiting the PI3K/AKT signaling pathway and causing hepatic steatosis, oxidative stress, inflammation, and cell apoptosis in chickens." (PMID 38539937, 2024). "Moreover, among the most significant signaling pathways related to DEGs in Rx‐Dicer mutants is the non‐alcoholic fatty liver disease pathway, headed by Irs2 (Table EV8)." (PMID 32985705, 2020). "This led to speculation that the decreased IRS-2 in hepatic steatosis is the main contributor to impairment of the insulin signaling that governs the suppression of hepatic glucose production." (PMID 29717275, 2018). "Furthermore, drugs used to treat T2DM, which also improve hepatic steatosis, such as rosiglitazone and metformin, are found to preferentially increase and restore IRS-2 expression." (PMID 22745692, 2012). "Our in vivo models of hepatic steatosis with perturbed insulin concentrations had relatively increased IRS-1 expression at high insulin concentrations (T2FLD), and relatively increased IRS-2 at low insulin concentrations (T1FLD)." (PMID 22745692, 2012). "GLP-1 ligands are able to promote the phosphorylation of AKT, an effect that subsequently triggers the postreceptor signaling cascade downstream of insulin receptor substrate-2 (IRS-2), leading to reduced storage of hepatocyte triglycerides and, therefore, reduced hepatic steatosis." (PMID 38979402, 2024).
lung cancer (16 papers, 2015 to 2025). A malignant neoplasm involving the lung. "Among all the tested genes, the top-performing ones were NUMA1 and JAK1 in KIRC, PDGFRB and BCL6 in lung cancer, IRS2 in endometrial cancer, and GNAS in BRCA, each with an AUC of at least 0.89." (PMID 38491101, 2024). "In lung cancer, tumors with low IRS-1 and high IRS-2 expression were associated with poor outcomes in adenocarcinoma and squamous cell carcinoma, indicating a potential role for IRS-2 in the aggressive behavior of non-small cell lung cancer." (PMID 36975518, 2023). "On the other hand, pharmacological JNK inhibition prevented NT157-induced IRS1 and IRS2 phosphorylation in both lung cancer cells studied." (PMID 36224313, 2022). "IRS2 (insulin receptor substrate-2) can be increased in cancer, including lung cancer, hepatocellular carcinoma (HCC), and breast and renal cancers, with the potential to regulate EMT pathways." (PMID 34359798, 2021). "It was found that miR-146a overexpression maintained epithelial phenotypes and discouraged epithelial to mesenchymal transition in lung cancer cell lines by suppressing insulin receptor substrate-2 (IRS2) transcription and translation." (PMID 33578944, 2021). "Yes‐associated protein has been previously reported to positively regulate insulin receptor substrate 2 (IRS2) to affect the activity of non‐small cell lung cancer cells, highlighting the relationship between YAP and IRS2." (PMID 33570213, 2021). "Previous studies have showed that miRNA-7 down-regulates the expression of EGFR and key modulators of the Akt pathway including IRS-1 and IRS-2 in glioblastoma, breast, cervical and lung cancer, which led to decreased cell survival and proliferation." (PMID 32592373, 2020). "At the mechanistic level, the pro-tumorigenic functions of DLX5 have been shown to involve positive regulation of the MYC promoter in human lung cancer cells as well as the IRS2 promoter, an IGFIR adapter protein, in ovarian cancer cell lines." (PMID 30412601, 2018). "A large number of studies have found that has-miR-338-3p inhibits the proliferation and invasion of lung cancer cells by targeting SOX4, IRS2 and AKT." (PMID 35992856, 2022). "miR-7 targets RAF1, IRS-2, BCL-2, and PA28γ in lung cancer cells." (PMID 33422052, 2021). "In addition, IRS2 amplification, firstly confirmed in a study of PI3K signaling pathway changes in colorectal cancer, has been a vital indicator of sensitivity to targeted therapy in colorectal and lung cancers." (PMID 38750402, 2024).
hepatocellular carcinoma (15 papers, 2012 to 2025). A malignant tumor that arises from hepatocytes. "In rat hepatoma cells, the mTOR pathway has been established as intricately linked to the phosphorylation of serine residues within IRS-2, particularly Ser907 and Ser675." (PMID 38248343, 2024). "When rat primary hepatocytes and HuH-7 human hepatoma cells were cultured in the Zero medium, IRS-2 protein levels increased compared to those cultured in the Full medium." (PMID 39859555, 2025). "In the present study, we found that IRS-2 protein levels increased in response to amino acid deprivation in both rat primary hepatocytes and HuH-7 human hepatoma cells." (PMID 39859555, 2025). "This phosphorylation event was observed in rat hepatoma cells, where a connection between the mTOR pathway and the phosphorylation of IRS-2 serine residues, specifically Ser907 and Ser675, was es-tablished." (PMID 38248343, 2024). "IRS2 is overexpressed in human and murine hepatocellular carcinoma, resulting in protection from apoptosis." (PMID 29868002, 2018). "IRS2 was also found overexpressed in human and mouse hepatocellular carcinoma cells, and down regulation of IRS2 expression increased apoptosis in these cells, suggesting that IRS2 can contribute to liver tumors." (PMID 29868002, 2018). "Insulin-stimulated interaction between endogenous IRS-2 and 14-3-3 was observed in rat hepatoma cells and in mice liver after an acute insulin stimulus and refeeding." (PMID 22912850, 2012). "Given that IRS2 is tightly involved in IGF1-induced cell migration, we then detected whether AFB1 could promote hepatoma cell migration through IGF-IR/IRS2 axis." (PMID 23112878, 2012). "IRS2 expression is up-regulated in hepatocellular carcinoma." (PMID 23112878, 2012). "Accumulated IRS2 may compensate for the loss of IRS1 and enhance hepatoma cell migration by modulating cell migration-promoting effectors that are shared or not shared by IRS1." (PMID 23112878, 2012). "IGF-IR inhibitor or IRS2 knockdown suppressed AFB1-induced hepatoma cell migration." (PMID 23112878, 2012). "In addition, in patients with hepatocellular carcinoma, deficiency of phosphatase and tensin homolog (PTEN) activated AKT, which activated YAP/TAZ, which in turn induced transcription of insulin receptor substrate 2 (IRS2)." (PMID 37927473, 2023). "Another report revealed that the HCV core protein in both transgenic mice or hepatoma cells downregulates IRS1 and IRS2 by upregulating SOCS3." (PMID 33849568, 2021). "Consistent with studies in other models, our current study show that AFB1 stimulates hepatoma cell migration in IGF-IR- and IRS2-dependent manner." (PMID 23112878, 2012). "Here, we report that AFB1 stimulates IGF-IR phosphorylation, down-regulates IRS1, but up-regulates IRS2 expression, which contributes to AFB1-induced hepatoma cell migration." (PMID 23112878, 2012). "Our current study demonstrates that AFB1 up-regulates IRS2 but down-regulates IRS1 levels in hepatoma cells, leading to a shift in IRS1 and IRS2 expression towards a high IRS2/IRS1 ratio." (PMID 23112878, 2012). "Up-regulation of IRS2 contributed to AFB1 induced activation of Akt and ERK1/2 thereby stimulating hepatoma cell proliferation and migration." (PMID 23112878, 2012). "Although one study showed that mTORC1 is required for insulin stimulation of serine phosphorylation of IRS-2 in Fao cells (hepatic carcinoma cells), S6K1 is not required for this effect." (PMID 39163364, 2024). "Since AFB1 induces IGF-IR phosphorylation, up-regulates IRS2, but down-regulates IRS1, it is unclear how AFB1 may affect hepatoma cell proliferation." (PMID 23112878, 2012). "Furthermore, the HCV core protein of genotype 3a promotes IRS1 (but not IRS2) degradation by upregulating SOCS7 in a human hepatoma cell line (Huh-7)." (PMID 33849568, 2021).
hepatocellular carcinoma (continued). "Treatment with MG132 significantly increased IRS2 levels but not IRS1 levels in HepG2 and SMMC-7721 cells treated without AFB1, indicating that IRS2 might undergo proteasomal degradation in AFB1-untreated hepatoma cells." (PMID 23112878, 2012).
colorectal cancer (14 papers, 2012 to 2025). A primary or metastatic malignant neoplasm that affects the colon or rectum. "Recent studies explored the association between insulin receptor substrate-2 (IRS-2) gene rs1805097 polymorphism and colorectal cancer (CRC) with contradictory findings." (PMID 28212577, 2017). "Increased IRS2 expression in colorectal cancer promotes tumor progression and invasion by activating the PI3 kinase pathway." (PMID 40141294, 2025). "The IGF2 gene and IRS2 gene are frequently gained in colon cancer and have been proposed as a colorectal cancer ‘driver’ oncogenes." (PMID 31526479, 2019). "IRS2 is a candidate driver oncogene that is frequently amplified in colorectal cancer and significantly positively correlated with IRS2 mRNA expression." (PMID 26684807, 2015). "The IRS2 polymorphism rs2289046(A>G), which is a 3′UTR SNP, has already been reported it is closely related to the onset of pancreatic, breast and colorectal cancer." (PMID 24497996, 2014). "Components of IGF-IR signaling pathway such as IRS1 and IRS2 have been demonstrated to have predictive value in IGF-IR-targeting therapies in preclinical models of breast and colorectal cancer." (PMID 28137302, 2017). "For example, in a survey of 41 breast and 27 colorectal cancer cell lines, the expression levels of IGF-1R, IRS-1, IRS-2, and IGF-2 were correlated with positive predictive values for h10H5." (PMID 22952934, 2012).